HIF1A (hypoxia inducible factor 1 subunit alpha)
Diseases named in the same sentence as HIF1A in open-access papers (continued):
Sharing a sentence is not in itself a finding about the gene and the disease.
pancreatic ductal adenocarcinoma (49 papers, 2013 to 2026). An infiltrating adenocarcinoma that arises from the epithelial cells of the pancreas. "Indeed, similar to our observations in the CCL7 3'UTR, a variant closely located to a miR-199a binding site at the 3'UTR of the HIF1A gene, is associated with pancreatic ductal adenocarcinoma risk and worse clinical outcomes." (PMID 35711383, 2022). "In pancreatic ductal adenocarcinoma, targeting the lactate and HIF1α signaling pathways from tumor cells attenuates radioresistance." (PMID 40469197, 2025). "In response to hypoxia, KRAS-activated pancreatic ductal adenocarcinoma cells presented with CAIX overexpression through the stabilization of HIF1A and HIF2A, as an adaptive process to maintain pH and glycolysis." (PMID 36768903, 2023). "Upon hypoxic conditions, pancreatic ductal adenocarcinoma cells exhibited elevated HIF1A and HIF2A expression levels, increased expression of carbonic anhydrase 9, and activated glycolysis." (PMID 36925652, 2023). "UBE2S was demonstrated to promote the epithelial-mesenchymal transition (EMT) through the VHL/HIF-1α/STAT3 signaling pathway in pancreatic ductal adenocarcinoma." (PMID 34535173, 2021). "This study aims to identify the molecular mechanism of recruiting monocytes/macrophages by HIF-1α in pancreatic ductal adenocarcinoma (PDAC) and the effects of macrophages on pancreatic stellate cells (PSCs)." (PMID 27271610, 2016). "Hypoxia-inducible factor-1 alpha (HIF-1α) is over-expressed in many cancers including pancreatic ductal adenocarcinoma (PDAC) and correlated with poor prognosis." (PMID 26872370, 2016). "Its down-modulation abolished pancreatic ductal adenocarcinoma cell invasion and metastasis by indirectly targeting HIF-1α." (PMID 27551267, 2016). "Stem cell factor (SCF) and hypoxia-inducible factor-1α (HIF-1α) both have important functions in pancreatic ductal adenocarcinoma (PDAC)." (PMID 25799412, 2015). "HIF-1α promotes glycolysis and inhibits of mitochondrial respiration in pancreatic ductal adenocarcinoma (PDAC)." (PMID 24662981, 2014). "Basic leucine zipper and W2 domains 1 is an adaptor for protein kinase RNA-like endoplasmic reticulum kinase, which in turn facilitates the phosphorylation of eIF2α to promote internal ribosome entry site (IRES)-dependent translation of HIF1α and c-Myc in human pancreatic ductal adenocarcinoma." (PMID 36435920, 2023). "We hypothesize that auranofin may prevent pancreatic ductal adenocarcinoma progression by inhibition of Txnrd1 and HIF-1α." (PMID 33981979, 2019). "Recent studies have demonstrated that HIF1α and YAP1 can establish a positive feedback loop, contributing to epithelial-to-mesenchymal transition in pancreatic ductal adenocarcinoma." (PMID 38602536, 2024). "Equally, treatment with the NRP2-specific mAb N2E4 inhibited pancreatic ductal adenocarcinoma cell tumor growth and metastasis by blocking interactions with β1 integrin to inhibit FAK/Erk/HIF1α/VEGF-A165 signaling." (PMID 36970722, 2022). "The real-time polymerase chain reaction (PCR) and Western blot analyses were performed to identify the expressions of HIF-1α and VEGF-A in pancreatic ductal adenocarcinoma cell lines." (PMID 33830713, 2021). "The prolyl 4-hydroxylase subunit alpha 1 (P4HA1) is critically involved in the glycolytic phenotype of pancreatic ductal adenocarcinoma (PDAC) cells, which can be transactivated by HIF-1α under hypoxic condition and further enhances HIF-1α stabilization." (PMID 33436044, 2021). "One report indicated that in pancreatic ductal adenocarcinoma (PDAC), HIF-1α promoted the secretion of MCP-1, enhanced monocyte and macrophage recruitment, and strengthened inflammation and fibrosis." (PMID 31623681, 2019). "Another important point is that LCN2 promotes HIF-1α and vascular endothelial growth factor (VEGF) expression in several pancreatic ductal adenocarcinoma cell lines which contributes to an increase in vascularity." (PMID 30871254, 2019).
pancreatic ductal adenocarcinoma (continued). "Pancreatic ductal adenocarcinoma (PDAC) has reactive stroma that promotes tumor signaling, fibrosis, inflammation, and hypoxia, which activates HIF-1α to increase tumor cell metastasis and therapeutic resistance." (PMID 30214007, 2018). "However, in the extremely hypoxic tumor microenvironment of pancreatic ductal adenocarcinoma, USP25 still deubiquitinate HIF-1α to abrogate its degradation." (PMID 36998063, 2023). "A previous study showed that pancreatic ductal adenocarcinoma (PDACs) cells that express an activated KRAS increase the expression of CA9, via stabilization of hypoxia-inducible factor 1 subunit alpha (HIF1A) and HIF2A, which eventually regulates the pH and glycolysis." (PMID 33456371, 2020). "In addition, high expression of HIF-1α, which is regulated by the LncRNA PVT1/miR-519d-3p axis, promotes glycolysis and pancreatic ductal adenocarcinoma progression." (PMID 33154192, 2020). "In pancreatic ductal adenocarcinoma (PDAC), it has been recently shown that genetic ablation of Hif1α accelerates tumour development by promoting tumour-supportive inflammation in mice, questioning its role as the key downstream target of many oncogenic signals of PDAC." (PMID 27941931, 2016). "Moreover, immunohistochemical (IHC) validation using tissue microarrays from 20 human pancreatic ductal adenocarcinoma (PDAC) specimens revealed that the overall expression of RASSF1C and hypoxia-inducible factor-1 alpha (HIF-1α) was higher than that of UFL1 and IRF7." (PMID 41912489, 2026). "Given that the mechanism of USP25 antagonism under this hypoxic condition was not described, whether there are other E3 ligases targeting HIF-1α that can be antagonized by USP25 in pancreatic ductal carcinoma deserves further investigation." (PMID 36998063, 2023). "In pancreatic ductal adenocarcinoma, lncRNA ENST00000480739 has been demonstrated to increase the levels of endoplasmic reticulum lectin protein, which is known to increase the affinity between HIF-1α and EGLN hydroxylases, therefore leading to HIF-1α destabilization." (PMID 28793797, 2018).
Alzheimer disease (47 papers, 2014 to 2026). A progressive, neurodegenerative disease characterized by loss of function and death of nerve cells in several areas of the brain leading to loss of cognitive function such as memory and language. "The BCL3, CFLAR, SMAD1, and HIF1A genes have been identified to be associated with late-onset Alzheimer's disease." (PMID 28558704, 2017). "Interestingly, an inverse association has been noted between cancer and Alzheimer’s Disease (AD) concerning PIN1 regulation of HIF-1α." (PMID 33383924, 2020). "Given its role in the key pathological processes of Alzheimer’s disease—including cerebral hypoperfusion, neuroinflammation, and impaired synaptic plasticity—HIF-1α emerges as a promising therapeutic target." (PMID 40722590, 2025). "C3AR1 depletion inhibits oxidative stress in microglia and mitigates HIF-1α-induced metabolic damage, thereby ameliorating cognitive dysfunction in Alzheimer’s disease." (PMID 40939011, 2025). "For instance, silencing or inhibiting HIF‐1α in microglia was beneficial in animal models of PD and Alzheimer's disease." (PMID 39888089, 2025). "The dysregulation of the HIF-1A pathway contributes to the development of various diseases, including cancer, cardiovascular disease, and Alzheimer's disease." (PMID 38443855, 2024). "Conversely, overexpression of HIF-1α in the brains of individuals with Alzheimer’s disease (AD) has been shown to inhibit the activation of insulin receptor substrate 1 in the neurons." (PMID 38731800, 2024). "Lf has also shown promise in ameliorating cognitive impairment in Alzheimer’s disease mouse models through HIF-1α activation." (PMID 38731800, 2024). "We compared this regulatory network with Alzheimer’s disease gene expression data and we perturbed the system by inducing or repressing the HIF1A protein in silico." (PMID 37626282, 2023). "KEGG pathway analyses conducted across microglia revealed terms of “Alzheimer’s disease,” “cholesterol metabolism,” and “HIF1α signaling” for the E4-enriched Mi_6 subset." (PMID 36871219, 2023). "Studies have shown that HIF-1α related signaling pathways regulate microglia activation in Alzheimer’s disease." (PMID 34497517, 2021). "Studies have shown that HIF-1α is involved in microglia activation in patients with Alzheimer’s disease." (PMID 34497517, 2021). "Patients with Alzheimer’s disease have been shown to have reduced levels of HIF-1α as well as glucose transporters and a decreased rate of aerobic glycolysis in the brain." (PMID 34395432, 2021). "Integrated models support HIF-1A as effective target to reduce the effects of hypoxia in Alzheimer’s disease." (PMID 31291905, 2019). "Donepezi, an acetylcholinesterase inhibitor, exhibits beneficial effects in Alzheimer’s disease through activation of the PI3K/Akt/HIF-1α/VEGF pathway." (PMID 29937713, 2018). "Furthermore, in Alzheimer’s disease (AD) models, increased expression of HIF1α correlates with a decline in cognitive function." (PMID 39717345, 2024). "In vitro and in vivo findings suggest that rAAV-mediated HIF-1α gene delivery may ameliorate amyloid-β (Aβ)-induced cognitive deficits by reducing hippocampal neuron apoptosis in Alzheimer’s disease models." (PMID 38731800, 2024). "CSC and CB microglia also express more GRID2, previously detected in brain microglia of Alzheimer’s disease donors, and more HIF1A and NEAT1, which may indicate a hypoxic stress response." (PMID 37217978, 2023). "Our studies identify a heightened C3aR/HIF-1α signaling axis that influences microglial metabolic and lipid homeostasis in Alzheimer disease, suggesting that targeting this pathway may offer therapeutic benefit." (PMID 37317973, 2023). "Increased expression of Hif1a is found in the DAM gene signature, and activation of microglia in Alzheimer’s disease mouse models is dependent on the mTORC1/HIF1A pathway, which leads to the glycolytic state." (PMID 40911604, 2025).
Alzheimer disease (continued). "HIF-1α and EPO receptor proteins are elevated in the hippocampus of patients with Alzheimer’s disease along with a decrease in GLUT1, GLUT3, and EPO protein." (PMID 35159233, 2022). "Thus, a good understanding of factors, including hypoxia (i.e., the biochemical implication of HIF-1α) and kynurenine pathway activation in NDs, focusing on Alzheimer's disease could prove beneficial to new therapeutic approaches for this disease, thus the aim of this review." (PMID 34804368, 2021). "Two well-documented examples of RNA masking focus on the bi-directionally transcribed genes BACE1 and HIF1α, both highly relevant to human disease, BACE1 in Alzheimer’s disease and HIF1α in cancer." (PMID 29209299, 2017). "Our results suggest demonstrate differential dose-dependent effects of simvastatin on HIF-1α and BACE in cultured Alzheimer’s disease cybrid cells." (PMID 26228060, 2015). "The increased expression of HIF1A, a hypoxia-inducible factor, suggests that FVSE enhances neuronal resilience by reducing oxidative stress and preserving mitochondrial function, which is critical in Alzheimer’s disease pathology." (PMID 39684414, 2024). "In conclusion, our result demonstrated that a pathological angiogenesis process and the levels of angiogenesis regulators, including PlGF and AngII, were increased in an Alzheimer’s disease mouse model at an earlier time when HIF-1α expression was not changed." (PMID 36901941, 2023). "In addition to the negative impact of HIF-1α overexpression, some studies indicated HIF-1α could be a neural protective factor in the progression of PD and Alzheimer’s disease (AD)." (PMID 36674945, 2023).
lymphoma (47 papers, 2013 to 2026). A malignant (clonal) proliferation of B- lymphocytes or T- lymphocytes which involves the lymph nodes, bone marrow and/or extranodal sites. "Direct inhibition of glycolysis with 2-deoxy-d-glucose (2-DG) reduced the production of lactate, similar results were observed with the inhibition of mTOR or HIF1α, and all three treatments were toxic to PD-1-deficient lymphoma cells." (PMID 37723306, 2023). "Human hematological malignant disease, including leukemia and lymphoma, express high levels of HIF-1α, which is often closely associated with poor disease prognosis." (PMID 34124226, 2021). "Indeed, pathogenic role of HIF-1α was observed in the specimen leukemic stem cells/lymphomas." (PMID 35870078, 2022). "Interestingly, mice carrying lymphoma and deficient for a gene (Hif1a) coding for a transcription factor useful for hypoxia adaptation also show reduced tumor growth in association with an increase in activated tumor-infiltrating NK cells (high expression of Ifng, Cd69, Prf1, Gzma and Gzmb)." (PMID 34680190, 2021). "Here we show that the pyruvate branch point operates as a metabolic checkpoint for lymphoid cancer cell migration and disease dissemination through mitochondrial ROS (mROS)/HIF-1a signaling." (PMID 41890071, 2026). "It has been reported that BCL2 expression in lymphoma cells induces hypoxia-inducible factor-1 alpha (HIF1α)-mediated expression of VEGF, an angiogenic factor that promotes endothelial cell proliferation and migration." (PMID 39735667, 2025). "In lymphoma, there is evidence of the activation of HIF-1α and c-Myc, as well as the activation of LDHA, MCT1, and MCT4." (PMID 39464313, 2024). "Tumor cells under hypoxic conditions overexpress HIF-1α, and not only solid tumors but also malignant lymphomas express high levels of HIF-1α, which is considered a poor prognostic factor." (PMID 39768123, 2024). "To test the dependency of fully transformed lymphomas with Pdcd1 deletion on the released mTOR–HIF1α–glycolysis cascade, we incubated ITK–SYK+PD-1− cells with small-molecule inhibitors of mTOR, HIF1α or glycolysis." (PMID 37723306, 2023). "PX-478 is a small-molecule inhibitor of HIF-1α and inhibits lymphoma cell growth even under normoxia." (PMID 36982568, 2023). "PCI-24781 is a broad-spectrum histone deacetylase inhibitor (HDACi) that can promote the accumulation of HIF-1α and induce initial autophagy of lymphoma cells." (PMID 36982568, 2023). "Echinomycin down-regulated MYC and HIF1α proteins despite increasing their mRNA levels in Eμ-Myc lymphoma cells." (PMID 33572152, 2021). "It would be interesting to examine such a double-target (HSP70 + HIF-1α) approach on the radiation response of hypoxic lymphomas." (PMID 33806538, 2021). "NF-κB-mediated HIF-1α, or vice versa, has been extensively documented in various conditions, including malignant lymphoma and immune responses." (PMID 34950652, 2021). "GNG7, AXIN2, HIF1A, FGF2 and PPAP2B are found upregulated in our study in the same way as it is found in association with lymphoma disease according to literature." (PMID 30679748, 2019). "In cultivated lymphoma cells, constitutive HIF-1α activity and vHL suppression were noted resulting in the maintenance of the cancer stem cell phenotype." (PMID 31824854, 2019). "HIF-1α presented predominantly with nuclear localization within the lymphoma cells, while the HIF-2α was more prominent in adjacent reactive macrophages." (PMID 31824854, 2019). "Lymphoma cells were grown at 21% and 5% O2 for 48 h to determine HIF1α levels in respective cell lines by immunocytochemical and Western blot analysis." (PMID 29949925, 2018). "Published molecular profiling studies in patients with lymphoma suggested the influence of hypoxia inducible factor-1 alpha (HIF1α) targets in prognosis of DLBCL." (PMID 29335581, 2018).